INS (insulin)
Diseases named in the same sentence as INS in open-access papers (continued):
Sharing a sentence is not in itself a finding about the gene and the disease.
Hyperglycemia (continued). "Surgeries of all kinds and post-operative pain have been long shown to increase risk of hyperglycemia by triggering cytokines and stress hormones known to aggravate insulin action." (PMID 25721247, 2015). "Considerable evidence implicates insulin resistance or hyperglycaemia as the mechanism by which maternal obesity causes excessive neonatal birth weight." (PMID 25588785, 2015). "Although glucose plays a critical role in the physiological response of insulin secretion in pancreatic beta cells, chronic hyperglycemia causes impaired glucose-induced insulin secretion, altered gene expression, and apoptosis of beta cells." (PMID 25938469, 2015). "A study previously reported that Orz reduced the risk of high-fat diet-induced hyperglycemia via regulation of insulin secretion as well as the activities of hepatic glucose-regulating enzymes such as G6Pase and phosphoenolpyruvate carboxykinase (PEPCK)." (PMID 26083118, 2015). "These have shown that pasireotide-associated hyperglycemia is related to decreases in insulin secretion and incretin hormone response." (PMID 23529827, 2014). "Alpha effects include arteriolar constriction causing hypertension and diminished insulin secretion and enhanced gluconeogenesis and glycogenolysis all of which promote hyperglycemia." (PMID 25215250, 2014). "This study demonstrated a significant association between DKA and the use of insulin regimens throughout the severe or acute hyperglycemia phase (p = 0.043), with DKA more common in cases in which sliding-scale insulin was used." (PMID 25181406, 2014). "Chronic hyperglycaemia was associated with a ~20-fold increase in cells positive for both insulin and glucagon (ins+/glu+ cells) in islets from 4-week-diabetic βV59M mice." (PMID 25145789, 2014). "Defects in beta cell function, including reduced insulin secretion and reduced efficiency of proinsulin conversion to insulin, are key pathophysiological factors underlying the hyperglycaemia of patients with type 2 diabetes mellitus." (PMID 24585202, 2014). "On the one hand, serious AMI can cause stress hyperglycemia, resulting from a surge of stress hormones such as adrenaline, noradrenalin, and cortisol which induce or exacerbate an insulin-resistant state." (PMID 25132854, 2014). "We also report herein the neutralization of the dermcidin-induced atherosclerotic risk by insulin and by aspirin via the synthesis of NO through the control of both hyperglycemia and hypertension." (PMID 24649391, 2014). "This supports the use of low glycemic index enteral nutrition for hospitalized patients, which would essentially smooth out carbohydrate absorption and decrease insulin requirements and lower risk of hyperglycemia, especially in sensitive populations." (PMID 24744913, 2014). "This suggests that, although hyperglycaemia can be controlled by appropriate insulin medication, some of the associated system irregularities persist." (PMID 25469509, 2014). "It has long been known that administration of excess amount of insulin to humans can cause hyperglycemia, which has been called the Somogyi phenomenon." (PMID 24741073, 2014). "T2DM is a complex heterogeneous group of metabolic disorders including hyperglycemia and impaired insulin action and/or insulin secretion, and a detailed etiology underlying T2DM is still unclear." (PMID 25561226, 2014). "Leptin in supraphysiological doses in vitro is known to block insulin interaction with its receptor on the cell membrane, which is associated with impaired insulin-mediated glucose transport, hyperglycaemia and more severe IR." (PMID 24433403, 2014). "In contrast, relative to controls, exposure of PERαKO−/− female mice to ALX, induced marked hyperglycemia and insulin deficiency that resulted from a more severe β-cell destruction (97%) and decrease in pancreatic insulin concentrations." (PMID 24498408, 2014).
Hyperglycemia (continued). "Chronic hyperglycaemia is associated with a dramatic reduction in insulin-positive cells and an increase in glucagon-positive cells in islets, without alterations in cell turnover." (PMID 25145789, 2014). "Mice deficient in Akt2 develop hyperglycemia and hyperinsulinemia and are impaired in their ability to lower blood glucose in response to insulin." (PMID 24722238, 2014). "Infants need extremely small doses of insulin and have a higher risk of hypoglycemia or hyperglycemia, which needs to be avoided because of the high risk of brain damage." (PMID 25052923, 2014). "The basic mechanism of HE is a reduction in the net effective action of circulating insulin, resulting in hyperglycemia and ketonemia (in DKA) causing osmotic diuresis and electrolytes loss." (PMID 25945127, 2014). "This endocrine disorder, characterized by hyperglycemia, is associated with disturbances of carbohydrate, fat and protein metabolism resulting from altered insulin sensitivity and impaired insulin secretion." (PMID 25364320, 2014). "GALNT2 is associated with lipid levels, insulin signaling, hyperglycemia, and the malignant behavior of hepatocellular carcinoma." (PMID 24906187, 2014). "Similar to dox-184 animals, Tg-04 and Tg-32 animals exhibited hyperglycemia and reduced circulating insulin due to loss of β cell mass and pancreatic insulin content." (PMID 24361012, 2014). "It is clear, however, that insulin production and secretion were indeed inhibited, as less insulin was being stored in rapa-treated mice and plasma insulin levels were reduced, likely the cause of the more severe hyperglycemia." (PMID 25473963, 2014). "Over time, the suffering pancreas becomes unable to produce enough insulin, leading to hyperglycemia and insulin deficiency that accompany T2DM in the end of its natural history." (PMID 24574966, 2014). "It usually takes years from an initial impairment of insulin action in peripheral tissues and liver with hyperglycemia, hyperinsulinemia to a progressive loss of β-cell responsiveness and finally complete loss of β-cell mass." (PMID 25106484, 2014). "In human pancreatitis, treatment is largely restricted to nutritional support, often accompanied by insulin therapy to reduce hyperglycemia-associated sepsis and systemic inflammation." (PMID 24993827, 2014). "Along with its insulin-mimetic effects, visfatin was as effective as insulin in inducing hyperglycemia in insulin deficient mice." (PMID 25593725, 2014). "Insulin appropriately controlled the hyperglycaemia in the colon and prevented the myenteric neuronal loss." (PMID 25469509, 2014). "DM is characterized by complete or partial deficiencies in insulin production and/or insulin action coupled with chronic hyperglycemia and disruption in metabolism." (PMID 25516848, 2014). "Another group using β-cell-Met−/− mice displayed mild hyperglycemia and a complete loss of acute-phase insulin secretion in response to glucose." (PMID 28548072, 2014). "Although hyperglycaemia can be controlled by appropriate insulin replacement, some of the associated irregularities persist in the different intestinal segments and influence the outcome of the therapies." (PMID 25469509, 2014). "DM is a group of metabolic diseases characterized by hyperglycemia caused by a diminished insulin secretion, insulin effect, or both." (PMID 25332855, 2014). "After ALX exposure, both control and PERαKO−/− male mice developed hyperglycemia and insulin deficiency and exhibited decreased β-cell mass and pancreatic insulin concentrations." (PMID 24498408, 2014). "Nevertheless the offspring were insulin resistant, impaired glucose tolerant and increased hepatic gluconeogenesis appeared to be a mechanism underlying fasting hyperglycemia." (PMID 25398136, 2014). "In conclusion, there is a complex relationship between the use of insulin analogs, hyperglycemia, and cancer risk." (PMID 24904529, 2014).
Hyperglycemia (continued). "Pancreatic islet cell death is one cause of deficient insulin production in diabetes mellitus and prevention of this cell death is an important prophylactic measure in the control and management of hyperglycemia." (PMID 24422903, 2014). "The resultant cells secreted insulin in response to changes in glucose levels in the physiological range and reversed hyperglycaemia when grafted into immune-deficient streptozotocin-induced diabetic mice." (PMID 24481872, 2014). "One of the adverse events associated with hypothermic therapy is a decrease in insulin sensitivity and insulin secretion, which can lead to hyperglycemia." (PMID 25097857, 2014). "Alterations of β-cell function and insulin properties underlay the metabolic syndrome that includes dyslipidemia, hyperglycemia, hypertension, impaired fibrinolysis, and atherosclerosis, thus contributing to lower insulin sensitivity." (PMID 24282409, 2013). "Insulin administration completely corrected the hyperglycemia-associated hypercalciuria and hypermagnesiuria, and reversed the increase of Ca and Mg transporter abundance." (PMID 23418599, 2013). "These self-reinforcing cycles between liver and pancreas eventually cause metabolic inhibition of insulin secretion after meals and onset of hyperglycaemia." (PMID 23075228, 2013). "As in the current study Bonner-Weir and colleagues also found that the prolonged hyperglycemia of adult STZ rats was associated with a decrease in insulin production." (PMID 24499555, 2013). "Both hypo- and hyperglycemia alter the coupling of glucose metabolism to insulin secretion, induce the loss of β-cell differentiation, and increase the rate of cell death." (PMID 24349266, 2013). "It is one of the most severe metabolic disorders in humans characterized by hyperglycemia due to a relative or an absolute deficiency of insulin or the resistance of target tissue to regulatory action of the hormone, or both." (PMID 24191197, 2013). "Elevated levels of endocannabinoids, such as 2-arachidonoylglycerol or anandamide, have been implicated in hyperglycemia and decreased insulin sensitivity in high fat fed mice and obese human subjects." (PMID 23835113, 2013). "Injectable insulin preserves life but perfect glucose control is difficult to achieve and chronic hyperglycemia-associated systemic damage takes its toll." (PMID 23826312, 2013). "Diabetes is a metabolic disorder characterized by hyperglycemia and caused by increased hepatic glucose production, abnormal glucose utilization in peripheral tissues, and inadequate insulin secretion." (PMID 23690865, 2013). "In rat aortic vascular smooth muscle cells, high glucose and chronic insulin treatment that mimicked hyperglycemia and hyperinsulinemia impaired iNOS induction by acute insulin treatment and was associated with sustained P38 activation." (PMID 23326243, 2013). "Hyperglycemia and perturbed insulin signaling have been proposed as pathogenic factors contributing to AD." (PMID 25050258, 2013). "Under insulin-resistant state, hepatic glycogen synthesis is diminished and is also associated with increased lipogenesis, which leads to hyperglycemia and contribute to the development of T2D." (PMID 24066304, 2013). "Diabetes mellitus is a multifactorial disease due to deficient insulin secretion and/or action, resulting in hyperglycemia, alterations in lipid metabolism, and a variety of complications in tissues throughout the body." (PMID 23585733, 2013). "The mechanisms underlying the development of hyperglycemia in sepsis remain poorly defined, and the protective role of endogenous insulin production versus the detrimental role of glucose toxicity continues to be controversial." (PMID 23826335, 2013). "Weight loss due to uncontrolled hyperglycemia was reversed in insulin gene treated diabetic rats to normal rate of weight gain, lasting ∼1 month." (PMID 23826312, 2013).
Hyperglycemia (continued). "Clinically, aggressive therapy with insulin seems to improve a host of metabolic and physiologic effects associated with acute hyperglycemia and appears to be warranted if euglycemia cannot otherwise be maintained." (PMID 24371503, 2013). "In diabetic conditions, hyperglycemia, hyperinsulinemia, and higher level of plasma free fatty acids are major metabolic alterations caused by the insufficient insulin actions to insulin-sensitive organs, hepatocytes, skeletal muscle cells, and adipocytes." (PMID 24455746, 2013). "STZ damages the pancreatic beta-cell initially causing release of insulin leading to a transient hyperinsulinemia/hypoglycemia and then resulting in longterm hypoinsulinemia/hyperglycemia." (PMID 24499555, 2013). "Lipid accumulation in the liver is commonly associated with liver and/or systemic insulin resistance and resultant hyperglycemia." (PMID 23826244, 2013). "Mice deficient of Fgl1 have fasting hyperglycemia, similar insulin sensitivity and enhanced gluconeogenesis." (PMID 23483972, 2013). "This chronic disease is characterized by hyperglycemia resulting from deficiencies in insulin secretion and/or insulin action." (PMID 23389304, 2013). "Hyperglycemia, resulting from rapidly absorbed glucose from a meal, will greatly stimulate insulin secretion, causing a large increase in plasma insulin." (PMID 23146593, 2012). "Regardless, during T2D, there is a chronic deficiency of glucose uptake and insulin action, mainly in the liver, skeletal muscle, and adipose tissue (AT), causing hyperglycemia, hypercholesterolemia, and hyperlipidemia." (PMID 23326021, 2012). "Physiologically, this is important as impaired insulin-mediated glucose disposal in subjects with chronic hyperglycemia would indicate a loss of glycemic control in postprandial periods." (PMID 22937169, 2012). "Plasma insulin secretion in response to intraperitoneal glucose injection was blunted in male diabetic TG mice, indicating that hyperglycemia was caused by impaired insulin secretion in these mice." (PMID 22384192, 2012). "As expected, HF feeding caused hyperglycemia, glucose intolerance, and impaired insulin sensitivity in wild‐type mice, as assessed by GTT and ITT." (PMID 23130157, 2012). "Hyperglycemia elicits the release of insulin from pancreatic beta cells causing increased cellular influx of glucose, thereby restoring the normal blood glucose level." (PMID 22954255, 2012). "Improvement of hyperglycemia and hyperlipidaemia is associated with a marked increase of insulin sensitivity." (PMID 21716678, 2012). "A diet high in fats and sugars (chronic hyperlipidemia and hyperglycemia) has also been linked to increased ER stress, particularly in the liver and in insulin-secreting β-cells of the pancreas (see the following)." (PMID 24278747, 2012). "It is characterized by absolute or relative deficiencies in insulin secretion and/or insulin action associated with chronic hyperglycemia and disturbances of carbohydrate, lipid, and protein metabolism (Duckworth, 2001 ▶)." (PMID 25050232, 2012). "Treatment with exogenous insulin is required to promote normal growth and avoid acute and sub-acute complications associated with severe hyperglycemia." (PMID 22781086, 2012). "These inflammatory cytokines inhibit insulin-stimulated glucose metabolism in skeletal muscles and stimulate gluconeogenesis in hepatocytes causing hyperglycemia." (PMID 22520940, 2012). "Reagents that interfere with insulin activities inevitably cause the adverse effect of hyperglycemia." (PMID 23152806, 2012). "The hyperglycemia associated with TB often aggravates the glycemic control of diabetics and thus warrants adjustment in the dose of insulin." (PMID 23497638, 2012). "In this cohort, the emerging use of insulin to manage hyperglycemia has carried a significant risk of hypoglycemia." (PMID 22871230, 2012).
Hyperglycemia (continued). "Similar to the results seen in the insulinoma SCID mouse model, SSTR1/5−/− mice developed temporal hyperglycemia associated with elevated basal glucose levels, lower insulin levels and an abnormal response to IPGTT seven days after the first treatment." (PMID 22905092, 2012). "Progressive deterioration in insulin sensitivity and reduction in pancreatic insulin secretion, create a state of relative insulin deficiency, resulting in hyperglycemia, presenting as impaired fasting glucose (IFG) at early stage or T2D at advanced stage." (PMID 21829658, 2011). "In the present study, we show that the hyperglycemia was only partially responsible for the loss of activity of the retinal insulin signaling pathway." (PMID 22046295, 2011). "We postulate that catecholamine overproduction in pheochromocytoma causes decreased insulin secretion and increased end-organ resistance, resulting in hyperglycaemia." (PMID 21226896, 2011). "As gluconeogenesis increases, as a result of hepatic insulin resistance, and relative insulin deficiency is exacerbated, hyperglycemia becomes more severe." (PMID 22110473, 2011). "Whilst differences between patients are acceptable, variable responses to the same insulin dose within the same patient can increase the risk of hypoglycaemia and hyperglycaemia." (PMID 21410860, 2011). "Type 1 diabetes is a T-cell mediated autoimmune disease leading to beta-cell destruction and loss of insulin secretion resulting in severe hyperglycemia." (PMID 21429197, 2011). "Type 1 diabetes is an autoimmune disease clinically characterized by hyperglycemia underlai by a significant loss of pancreatic insulin-producing beta cell mass." (PMID 21785616, 2011). "As expected, diabetic state induced by STZ was associated with severe hyperglycemia and hypoinsulinemia and low insulin positivity in the pancreas of rats 1, 2, or 4 months after STZ administration." (PMID 21792353, 2011). "In this model, mild hyperglycemia appears between 2 and 3 months of life, together with a partial deficiency in insulin." (PMID 19584081, 2011). "Nevertheless, a good metabolic control is difficult to reach and insulin therapy is frequently associated with severe episodes of hypoglycemia and hyperglycemia." (PMID 21304603, 2011). "This patient was at risk for hypoglycemia from a standard insulin sliding scale, in which the same graded doses of insulin is given to correct for hyperglycemia in all patients." (PMID 23882328, 2011). "Treating daytime hyperglycemia with basal insulin will increase the risk for nighttime or early morning hypoglycemia." (PMID 23882328, 2011). "Physiologically, GABA acts synergistically with insulin to inhibit the secretion of glucagon by the pancreatic α-cells, and reverse insulin-deficiency-related hyperglycemia in mice." (PMID 21966503, 2011). "Treatment of hyperglycemia with insulin infusion was associated with an increased rate of complications (OR 2.7, 95% CI 1.3–5.6, P = 0.01), although not statistically significant for death." (PMID 20811546, 2011). "The results of this retrospective follow-up study suggest that hyperglycemia and insulin therapy are not only associated with increased mortality and short term morbidity, but also exert long term effects on development." (PMID 20646308, 2010). "This association seems to be mediated by favorable changes in the lipid profile, but also by improvements in insulin action and lower risk for hyperglycemia." (PMID 20920226, 2010). "ICU patients are insulin resistant and too much exogenous glucose increases the risk of hyperglycemia, in particular as maximum glucose oxidation capacity is reduced to 2 to 5 mg/kg/minute." (PMID 20840773, 2010). "Sleep disturbance directly leads to glucose intolerance and hyperglycemia and, on the long term, to weight loss accompanied with reduced insulin responses." (PMID 20339560, 2010).